APP (amyloid beta precursor protein)
Diseases named in the same sentence as APP in open-access papers (continued):
Sharing a sentence is not in itself a finding about the gene and the disease.
Alzheimer disease (continued). "The pathological involvement of amyloid precursor protein (APP) in Alzheimer’s disease (AD) has been widely documented in the last 30 years due to its involvement in the generation of β-amyloid (Aβ) peptide." (PMID 37629148, 2023). "The amyloid precursor protein (APP), a key player in Alzheimer’s disease (AD), is part of a larger gene family, including the APP like proteins APLP1 and APLP2." (PMID 37533067, 2023). "In contrast to late-onset Alzheimer’s disease, early-onset Alzheimer’s disease (EOAD) is often caused by autosomal-dominant mutations, specifically in APP, PSEN1, and PSEN2." (PMID 37341843, 2023). "The accumulation of Aβ-peptides in senile plaques—observed in Alzheimer’s disease—is the consequence of erroneous processing of APP." (PMID 37445593, 2023). "The CP circadian clock was affected by age and Aβ deposition in the Alzheimer’s disease animal model consisting of APP/PS1 mice." (PMID 37628722, 2023). "Regarding Alzheimer’s disease, pharmacological modulation of APP by downregulating NUMB has been proposed as a novel therapeutic strategy." (PMID 36672267, 2023). "Mutations in the amyloid-β precursor protein (APP) and Presenilin 1/2 (PSEN1/2) genes cause Familial forms of Alzheimer’s disease (FAD)." (PMID 37257821, 2023). "Given the apparent importance of APP processing in the pathogenesis of Alzheimer’s disease, we next assessed the ability of a transgenic construct encoding the secreted extracellular domain of Appl37 to influence neuronal proteostasis." (PMID 37923712, 2023). "For example, in Alzheimer’s disease, Aβ peptide originating from the fragmentation of amyloid precursor proteins (APP) accumulates in the brain in the form of senile plaques." (PMID 37259454, 2023). "Since OGA inhibition is being considered for long-term AD treatment, we replicated OGA inhibition for 1 month in the 5XFAD Alzheimer’s disease mice which express high APP protein levels." (PMID 37469955, 2023). "EGCG is shown to increase α-secretase activity and hydrolysis of the TNF-α-converting enzyme to promote the cleavage of the α-c terminal fragment of APP in a model of Alzheimer’s disease." (PMID 36829922, 2023). "Mitophagy induced by UMI-77 ameliorates cognitive decline and amyloid pathology in the APP/PS1 mouse model of Alzheimer’s disease." (PMID 37582956, 2023). "An animal experiment found that the targeted deletion of YKL-40 suppressed glial phagocytic activation and promoted amyloid accumulation in a mouse APP/PS1 model of Alzheimer's disease." (PMID 36880855, 2023). "Previous studies have shown that ovocystatin improves cognitive function in young rats, prevents aging-related cognitive impairment in older animals, and induces changes in the expression of Alzheimer’s disease—Aβ and tau proteins in the APP/PS1 mice model." (PMID 36982505, 2023). "Melatonin, a neurohormone essential for functioning of the clock, was reported be able to reduce the production of amyloid plaques in N2a/APP cells and has the protective effect on Alzheimer's disease." (PMID 36875407, 2023). "Defective processing and secretion of specific proteins, such as the Amyloid Precursor Protein (APP), is associated with neurodegenerative diseases, including Alzheimer’s Disease." (PMID 37844085, 2023). "For instance, β-amyloid (Aβ) peptides generated from sequential cleavage of amyloid precursor protein (APP) by β-site APP-cleaving enzyme 1 (BACE1) play a key role in the pathogenesis of Alzheimer’s disease." (PMID 38139428, 2023). "For instance, accumulated amyloid precursor protein (APP) within mitochondria from individuals with Alzheimer's disease interacts with the protein channel components of both outer and inner membranes: TOM40 and TIM23 (TOMM40 and TIMM23)." (PMID 37303235, 2023). "GRk3 also improved spatial learning and reduced memory deficits in an amyloid precursor protein (APP)/presenilin 1 (PS1) double transgenic mouse model of Alzheimer’s disease (AD)." (PMID 38139116, 2023).
Alzheimer disease (continued). "The amyloid precursor protein (APP) is a key player in Alzheimer`s disease (AD) and the precursor of the Aβ peptide, which is generated by consecutive cleavages of β- and γ-secretases." (PMID 37259128, 2023). "This study aims to investigate sex and age differences in the characterization of periodontal bone tissue, immune state and cognitive function in amyloid precursor protein/presenilin 1(APP/PS1) murine model of Alzheimer’s disease (AD)." (PMID 37370108, 2023). "Apolipoprotein E (apoE) interaction with amyloid β-protein precursor (APP) has garnered attention as the therapeutic target for Alzheimer’s disease (AD)." (PMID 37211092, 2023). "The amyloid precursor protein (APP) is known as a precursor protein of Alzheimer’s disease (AD)-related amyloid β-protein (Aβ)." (PMID 37372424, 2023). "The amyloid precursor protein (APP) processing is well studied in the context of Alzheimer’s disease (AD) since this substrate cleavage results in the production of β-amyloid (Aβ)." (PMID 36904854, 2023). "Hesperidin (100 mg/kg) inhibited inflammation in an Alzheimer’s disease (AD) APP/PS1 mouse model, restored APP synthesis and Aβ peptide deposition, and improved nesting and social interactions." (PMID 37229273, 2023). "The pathogenesis of Alzheimer’s disease (AD) is believed to involve the accumulation of amyloid-β in the brain, which is produced by the sequential cleavage of amyloid precursor protein (APP) by β-secretase and γ-secretase." (PMID 38066066, 2023). "Numerous studies have focused on the pathophysiological role of amyloid precursor protein (APP) because the proteolytic processing of APP to β-amyloid (Aβ) peptide is a central event in Alzheimer’s disease (AD)." (PMID 37629148, 2023). "The major proteins involved in Alzheimer’s disease (AD) are amyloid precursor protein (APP) and Tau." (PMID 37569901, 2023). "About 2% of Alzheimer’s disease (AD) cases have early onset (FAD) and are caused by mutations in either Presenilins (PSEN1/2) or amyloid-β precursor protein (APP)." (PMID 37257821, 2023). "In the recent ten years, UBQLN1 is found to participate in neurodegenerative disease development, such as Alzheimer’s disease (AD), by regulating the maturation of full-length amyloid precursor protein (APP)." (PMID 37463174, 2023). "Citalopram, an SSRI, exerts protective effects on mitophagy in a transgenic mouse model of Alzheimer’s disease (AD) expressing amyloid precursor protein (APP)." (PMID 37869512, 2023). "Amyloid precursor protein (APP) is one of the major interests in current research on Alzheimer's disease (AD) since the aberrant processing of APP contributes to the generation and accumulation of neurotoxic peptide amyloid-β (Aβ)." (PMID 37387352, 2023). "Similar gut-brain connections have been found in other models of Alzheimer’s disease (AD), such as APP/PS1 and 5xFAD mice, as well as in normal aging mice." (PMID 38260869, 2023). "The processing of the amyloid precursor protein (APP) is one of the key events contributing to Alzheimer’s disease (AD) etiology." (PMID 36930302, 2023). "In a mouse model of Alzheimer’s disease expressing chimeric mouse/human amyloid precursor protein and mutant human presenilin-1 (APP/PSI), 10 cGy and 100 cGy 56Fe ion radiation resulted in decreased cognitive abilities 6 months later." (PMID 36388106, 2022). "Alzheimer’s disease is characterized by the presence of neuritic plaques, which primarily consist of Aβ peptides derived from APP proteolysis." (PMID 36418293, 2022). "Mutations in the genes for the amyloid-β precursor protein (APP) and the presenilins (PSEN1 and PSEN2) cause early-onset, dominantly inherited forms of Alzheimer’s disease (AD), whereas mutations in the MAPT gene mainly lead to frontotemporal dementia (FTD)." (PMID 35120450, 2022).
Alzheimer disease (continued). "Complementary multi-omics approach, in silico metabolic flux, and neuroimaging analyses link the sphingolipid pathway to Alzheimer’s disease pathogenesis with therapeutic targets validated using behavioral assessments in amyloidogenic APP/PS1 mice." (PMID 36209301, 2022). "Neurons exposure to Aβ oligomers led to an increase in the number of lysosomes, a decrease in the fraction of moving lysosome and an increase in their size, reminiscent of that found in APP transgenic model of Alzheimer’s disease." (PMID 35470226, 2022). "Under pathological conditions such as in Alzheimer’s disease and Down syndrome, altered amyloidogenic pathway and increased APP dose promote Aβ accumulation, Aβ aggregation, as well as the formation of insoluble fibrils into amyloid plaques." (PMID 36568886, 2022). "In a study using a transgenic APP/PS1 mouse model of Alzheimer’s disease, TargetScanTM analysis identified a potential binding site for miR-204-3p in the 3′-UTR of NOX4." (PMID 36670932, 2022). "Increased expression of APP leads to Alzheimer’s disease, where Aβ directly contributes to pathologies." (PMID 35360155, 2022). "Porphyromonas gingivalis infection in the transgenic mouse model of Alzheimer’s disease (APP-Tg) increased the deposition of Aβ and the levels of inflammatory cytokines in the brain." (PMID 35783096, 2022). "Mutations in the APP, Presenilin 1 (PSEN1), and Presenilin 2 (PSEN2) genes are known to be a cause of early-onset forms of Alzheimer’s disease, termed familial Alzheimer’s disease (fAD)." (PMID 35013145, 2022). "In this study, we provide evidence that over-expression of mutant forms APP/PS1 in a most commonly studied 5XFAD mice model for Alzheimer’s disease disrupts the trajectory or early cortical circuit development." (PMID 36075886, 2022). "Familial Alzheimer’s disease (FAD), caused by mutations in Presenilin (PSEN1/2) and Amyloid Precursor Protein (APP) genes, is associated with an early age at onset (AAO) of symptoms." (PMID 35365805, 2022). "It was found that the presence of amyloid precursor protein (APP) is an important element of the Alzheimer disease–presenilin pathway in human sperm and testis." (PMID 35327169, 2022). "Amyloid precursor protein (APP) is a protein that has a role in the progression of Alzheimer's disease." (PMID 36302939, 2022). "Deficiency of p38α‐MAPK in myeloid cells, but not only in microglia, efficiently attenuates cerebral Aβ and improves cognitive function in APP‐transgenic Alzheimer's disease mice." (PMID 35909315, 2022). "The β- and γ-secretase-driven cleavage of the amyloid precursor protein (APP) gives rise to the amyloid β peptide, which is believed to be the main driver of neurodegeneration in Alzheimer’s disease (AD)." (PMID 35563046, 2022). "In contrast, in the APP/PS1 Alzheimer’s disease mouse model, microglia increase production of the IL-12 and IL-23 subunit p40, and neutralization of p40 by antibodies reduces the cerebral amyloid load." (PMID 36293430, 2022). "Autosomal dominant Alzheimer’s disease (ADAD) accounts for approximately 1% of all Alzheimer’s disease (AD) cases and is usually caused by mutations in one of three known genes, namely PSEN1 (OMIM 104311), APP (OMIM 104760), and PSEN2 (OMIM 1600759)." (PMID 36380395, 2022). "In the APP/PS1 transgenic mouse model of Alzheimer’s disease (AD), Gal-3 interacts with amyloid-β and promotes its oligomerization." (PMID 36479526, 2022). "We also show that these ATase inhibitors can rescue disease manifestations associated with the progeria-like phenotype of AT-1 sTg mice, as well as the proteopathy of the Alzheimer’s disease (AD)-like phenotype of APP/PS1 mice." (PMID 35217767, 2022). "Amyloid precursor protein (APP) has been shown to interact with the N-terminal part of hAQP1 in Alzheimer’s disease brains via its C-terminal fragment, amyloid-beta (Aß)." (PMID 36077012, 2022).
Alzheimer disease (continued). "In the nervous system, hnRNP C binds with a 29-nt sequence in the 3′-UTR of amyloid precursor protein (APP) mRNA, whose cleavage product Aβ is highly correlated with degenerative neuropathy, such as Alzheimer’s disease, and regulates neuronal synapse growth." (PMID 35395937, 2022). "The resulting increase in the availability of peripheral irisin improved the cognitive performance of mice in two transgenic models of Alzheimer’s disease (APP/PS1 and 5xFAD), which was also accompanied with reduced glia activation." (PMID 36776770, 2022). "In the APP/PS1 mouse model of Alzheimer’s disease, the MAO-B activity is potentiated in hippocampal astrocytes, resulting in an elevated [GABA]i." (PMID 36555501, 2022). "Similar up- and down-regulated transcripts were observed in models of disease, particularly Alzheimer’s disease (AD), including APP/PS1 mice, 5XFAD mice and AppNL–G–F mice." (PMID 35875349, 2022). "In another study, the effect of NR on Alzheimer’s disease was evaluated using the APP/PSEN1 AD mouse model." (PMID 35918544, 2022). "Our main aim was to investigate some proteins involved both in the physiopathology of Alzheimer’s disease and in the neuronal migration process using the APP/PS1 Alzheimer’s mouse model." (PMID 34894324, 2022). "Most importantly, Tau reduction with AAV ZFP-TFs was able to rescue neuronal damage around amyloid plaques in a mouse model of Alzheimer’s disease (APP/PS1 line)." (PMID 36324900, 2022). "Elevated cholesterol levels induce accelerated APP processing in its amyloidogenic pathway, a condition related to the development of Alzheimer's dementia." (PMID 35411714, 2022). "As a potential biomarker with the highest PageRank scores, amyloid precursor protein (APP) is a substrate of proteases and secretase, which is mainly focused on pathogenesis of Alzheimer’s disease, was reported been involved in pancreatic cancer." (PMID 35711911, 2022). "Here we demonstrate in amyloid-β precursor protein (APP) transgenic mice and in patients with Alzheimer’s disease that medin co-localizes with vascular amyloid-β deposits, and that in mice, medin deficiency reduces vascular amyloid-β deposition by half." (PMID 36385530, 2022). "In vivo visualization of the hyperphosphorylative state by M-MRI was further validated in a second mouse model (APP/PS1) of Alzheimer's disease again identifying the mutants at a pre-pathological stage." (PMID 35910789, 2022). "If we consider the case of the APP protein, which is the precursor of the β-amyloid peptide of Alzheimer’s disease, we cannot use the 3D structure proposed by AlphaFold2 because it absolutely does not respect membrane topology." (PMID 36291736, 2022). "Trisomy of chromosome 21 in Down’s syndrome (DS) leads to three copies of APP and a concurrent high incidence of Alzheimer’s disease in DS patients." (PMID 35360155, 2022). "As a control, DAPT also blocked secretion of the Alzheimer's disease‐linked Aβ peptide from HEK293 cells transfected with C99, a C‐terminal fragment of the amyloid precursor protein (APP) that is an established substrate for γ‐secretase." (PMID 36069059, 2022). "Previous reports suggested that the interaction between APP, COPA, and CD74 is often associated with neurodegenerative diseases, such as Alzheimer's disease." (PMID 35525962, 2022). "Stabilization of complexes in which γ-secretase progressively cleaves APP is another promising approach toward the development of drugs to treat Alzheimer’s disease." (PMID 35471152, 2022). "The focus here is on investigating neurodevelopmental deficits in this model of early fetal brain development, but we also briefly examined a neurodegenerative-related pathology linked to triplication of the chr21 APP gene and early onset Alzheimer Disease (AD)." (PMID 36817096, 2022). "MA mitigated the gut microbiota changes in the APP/PS1 Alzheimer's disease mouse group, and the cognitive function and the intestinal barriers were also improved in the MA treatment group." (PMID 36712435, 2022).
Alzheimer disease (continued). "Amyloid precursor protein (APP) is associated with both familial and sporadic forms of Alzheimer’s disease." (PMID 34997052, 2022). "By inducing insulin resistance using a high-fat diet in an Alzheimer’s disease mouse model (APP/PS1), neuroinflammation and Aβ pathology were more severe compared to mice from the normal diet group." (PMID 35917087, 2022). "Here we tested each of these approaches for temporal and spatial control over transgenic APP expression to model the brain amyloidosis of Alzheimer's disease." (PMID 35394029, 2022). "BACE1 codes for an enzyme, beta secretase, which catalyzes the aberrant cleavage of amyloid precursor protein (APP), leading to APP aggregation, a hallmark of Alzheimer’s disease." (PMID 38596700, 2022). "The APP gene was also found in the networks and will be further discussed due to its role in Alzheimer’s disease." (PMID 36423114, 2022). "Together, these data indicate that enhancement of APP trafficking to the plasma membrane via light flicker plays a critical modulatory role in reduction of Aβ load in Alzheimer's disease." (PMID 35199454, 2022). "Several studies have reported that HAT members modulate neuronal fate: for example, enhanced p3000 HAT activity upregulated PKCδ-mediated neuronal apoptosis, and increased Tip60 HAT activities induced APP-mediated apoptosis in Alzheimer’s disease." (PMID 36309909, 2022). "Transplantation of the gut microbiota from Alzheimer’s disease patients into APP/PS1 double transgenic mice as a model of the disease increased expression of NLRP3 and led to more severe cognitive impairment." (PMID 35631301, 2022). "Immunostaining results indicate that ginsenoside F1 reduces Aβ plaques in the hippocampus of APPswe/PSEN1dE9 (APP/PS1) double-transgenic Alzheimer’s disease (AD) mice." (PMID 35054451, 2022). "In our research into Alzheimer’s disease, the ability to take a snapshot of the RNA environment allows us a unique insight into AD pathology, both in the APP/PS1 mouse model and in human post-mortem brain tissue." (PMID 35022475, 2022). "For example, gut microbiota shifts toward higher abundances of Proteobacteria in the transgenic APP/PS1 mouse model of Alzheimer's disease." (PMID 35308288, 2022). "In summary, iron can affect the progression of Alzheimer’s disease by regulating amyloid (Aβ), amyloid precursor protein (APP), and hyperphosphorylated tau." (PMID 35408967, 2022). "A recent study has shed light on a new formation mechanism of mosaicism for structural variations involving the APP gene in the Alzheimer’s disease brain, i.e. somatic gene recombination in neurons." (PMID 36266706, 2022). "Adeno-associated viral vectors were used to overexpress Gas6 in the APP/PS1 model of Alzheimer’s disease." (PMID 35130912, 2022). "Familial Alzheimer's disease (FAD) is caused by autosomal dominant mutations in the PSEN1, PSEN2 or APP genes, giving rise to considerable clinical and pathological heterogeneity in FAD." (PMID 34319632, 2022). "The APP/PS1 mouse model of Alzheimer’s disease shows cognitive deficits as early as 8 months of age." (PMID 36040311, 2022). "In established animal models of Alzheimer’s disease, the APP/PS1 mice (a transgenic mouse model of AD), expresses the human Swedish mutated form of APP and a mutated human form of PS-1." (PMID 36076972, 2022). "APP misexpression plays a crucial role in triggering a complex pathological cascade, leading to Alzheimer’s disease (AD)." (PMID 35223832, 2022). "For a prevalent neurodegenerative disease, Alzheimer’s disease, the iPSC-derived neurons from familial cases, sporadic cases, and healthy controls demonstrated the correlation between amyloid precursor protein (APP) proteolytic processing and P-tau." (PMID 36551987, 2022). "Second, the APP/PS1 transgenic mice are a model referring to the sporadic form of Alzheimer’s disease." (PMID 35566501, 2022).